ZNF747 (zinc finger protein 747)
Synonyms: MGC2474
Tractability: No criterion of Open Targets' tractability assessment is met for any kind of drug.
Gene: Protein-coding gene on chromosome 16 (30,530,367 to 30,535,347, reverse strand). Ensembl gene ENSG00000169955.
Subcellular location (Human Protein Atlas): Centrosome; Cytosol
Pathways (Reactome):
Gene expression (Transcription): Generic Transcription Pathway
Gene Ontology:
Molecular function: protein binding; DNA-binding transcription repressor activity, RNA polymerase II-specific; RNA polymerase II cis-regulatory region sequence-specific DNA binding
Biological process: negative regulation of transcription by RNA polymerase II; regulation of DNA-templated transcription
Cellular component: nucleus
Genetic constraint (gnomAD): Loss-of-function variants: 14 observed, 11.54 expected, observed/expected ratio (o/e) 1.21, 90% interval 0.8 to 1.8. The upper end of that interval is the gene's LOEUF score, 1.8, which puts it in group 6 of 6, group 1 being the genes least tolerant of losing a copy. Missense variants: 532 observed, 423.26 expected, observed/expected ratio (o/e) 1.26, 90% interval 1.17 to 1.35. Synonymous variants: 212 observed, 174.74 expected, observed/expected ratio (o/e) 1.21, 90% interval 1.08 to 1.36.
Homologues: Orthologues: chimpanzee ZNF747 (98% identical), rat Zfp764l1 (59% identical), mouse Zfp764l1 (58% identical), rat Zfp764 (58% identical), mouse Zfp764 (53% identical), zebrafish znf646 (21% identical), zebrafish si:dkey-89b17.4 (20% identical), Drosophila melanogaster CG18011 (18% identical), Drosophila melanogaster az2 (14% identical), zebrafish znf576.1 (14% identical), Drosophila melanogaster mld (12% identical), zebrafish si:ch211-148l7.4 (12% identical), and 8 more. Paralogues in human: ZNF764 (83% identical), ZNF785 (41% identical), ZNF689 (40% identical), ZNF688 (36% identical), ZFP92 (27% identical), ZNF420 (24% identical), ZBTB24 (23% identical), ZNF160 (23% identical), ZNF91 (23% identical), ZNF574 (23% identical), ZNF142 (22% identical), ZNF282 (22% identical), and 24 more.
Diseases named in the same sentence as ZNF747 in open-access papers:
ZNF747 is named in the same sentence as 1 disease in open-access papers, as found by Europe PMC text mining. Sharing a sentence is not in itself a finding about the gene and the disease. The quoted sentences say what the papers report.
breast carcinoma (1 paper, 2019). "Among the 1080 TCGA breast-cancer cases, there was little or no DNA mutations in IGKV2.30, IGKV.1 or ZNF747 genes." (PMID 30911020, 2019).